TGFBRAP1 (transforming growth factor beta receptor associated protein 1)
Description:
Plays a role in the TGF-beta/activin signaling pathway. It associates with inactive heteromeric TGF-beta and activin receptor complexes, mainly through the type II receptor, and is released upon activation of signaling. May recruit SMAD4 to the vicinity of the receptor complex and facilitate its interaction with receptor-regulated Smads, such as SMAD2. Plays a role in vesicle-mediated protein trafficking of the endocytic membrane transport pathway. Believed to act as a component of the putative CORVET endosomal tethering complexes which is proposed to be involved in the Rab5-to-Rab7 endosome conversion probably implicating MON1A/B, and via binding SNAREs and SNARE complexes to mediate tethering and docking events during SNARE-mediated membrane fusion. The CORVET complex is proposed to function as a Rab5 effector to mediate early endosome fusion probably in specific endosome subpopulations. Functions predominantly in APPL1-containing endosomes and in degradative but not recycling trafficking of endocytosed cargo.
Synonyms: TRAP-1; TRAP1; VPS3
Tractability: PROTAC: ubiquitination databases record sites on it; its protein half-life has been measured.
Gene: Protein-coding gene on chromosome 2 (105,264,359 to 105,329,735, reverse strand). Ensembl gene ENSG00000135966.
Subcellular location: Cytoplasm; Early endosome
Subcellular location (Human Protein Atlas): Vesicles
Gene Ontology:
Molecular function: protein binding; SMAD binding; transforming growth factor beta receptor binding
Biological process: endosomal vesicle fusion; endosome to lysosome transport; regulation of DNA-templated transcription; signal transduction; regulation of SNARE complex assembly; transforming growth factor beta receptor signaling pathway; intercellular transport; intracellular protein transport; vesicle-mediated transport
Cellular component: early endosome; membrane; CORVET complex; cytoplasm; endomembrane system
Genetic constraint (gnomAD): Loss-of-function variants: 20 observed, 83.97 expected, observed/expected ratio (o/e) 0.24, 90% interval 0.17 to 0.35. The upper end of that interval is the gene's LOEUF score, 0.35, which puts it in group 1 of 6, group 1 being the genes least tolerant of losing a copy. Missense variants: 950 observed, 1,132.9 expected, observed/expected ratio (o/e) 0.84, 90% interval 0.79 to 0.88. Synonymous variants: 415 observed, 471.04 expected, observed/expected ratio (o/e) 0.88, 90% interval 0.81 to 0.96.
Homologues: Orthologues: chimpanzee TGFBRAP1 (99% identical), macaque TGFBRAP1 (96% identical), rat Tgfbrap1 (90% identical), mouse Tgfbrap1 (89% identical), dog TGFBRAP1 (89% identical), guinea pig TGFBRAP1 (87% identical), pig TGFBRAP1 (87% identical), rabbit TGFBRAP1 (86% identical), tropical clawed frog tgfbrap1 (66% identical), zebrafish tgfbrap1 (63% identical). Paralogues in human: VPS39 (24% identical).
Diseases named in the same sentence as TGFBRAP1 in open-access papers:
TGFBRAP1 is named in the same sentence as 19 diseases in open-access papers, as found by Europe PMC text mining. Sharing a sentence is not in itself a finding about the gene and the disease. The quoted sentences say what the papers report.
hepatocellular carcinoma (2 papers, 2019 to 2024). A malignant tumor that arises from hepatocytes. "MiR-122 might inhibit hepatocellular carcinoma progression by downregulating TGFBRAP1 in the presence of the hepatitis C virus core, suggesting that the TGF-β/smad signalling pathway may be related to the expression level of miR-122, which plays an important role in drug-induced liver injury." (PMID 31534460, 2019). "As such, TGFBRAP1 expression is correlated with TGFΒR1 levels and TGF-β signaling activity in hepatocellular carcinoma (HCC) tissues, as well as overall survival and disease recurrence in multiple HCC cohorts." (PMID 38981014, 2024).
pulmonary fibrosis (2 papers, 2023 to 2024). Chronic progressive interstitial lung disorder characterized by the replacement of the lung tissue by connective tissue, leading to progressive dyspnea, respiratory failure, or right heart failure. "Article: Lee C-M, He C-H, Park JW, Lee JH, Kamle S, Ma B, Akosman B, Cotez R, Chen E, Zhou Y, Herzog EL, Ryu C, Peng X, Rosas IO, Poli S, Bostwick CF, Choi AM, Elias JA, Lee CG (2019 May 13) Chitinase 1 regulates pulmonary fibrosis by modulating TGF-β/SMAD7 pathway via TGFBRAP1 and FOXO3." (PMID 37037591, 2023). "Chitinase 1 (CHIT1) plays a role in the pathogenesis of pulmonary fibrosis by modulating canonical and noncanonical TGF-β signaling via interaction with TGFBRAP1 and FOXO3." (PMID 37037591, 2023).
diabetes (1 paper, 2019). "Our findings suggest that genetic polymorphisms of TGFBRAP1 may contribute to the genetic susceptibility of T2DM by mediating diabetes‐related miRNA expression." (PMID 30461200, 2019). "In conclusion, our findings suggest that genetic polymorphisms of TGFBRAP1 may contribute to the genetic susceptibility to T2DM by mediating diabetes‐related miRNA expression." (PMID 30461200, 2019). "A case‐control was conducted to evaluate the associations of the polymorphisms of TGF‐β1 receptor‐associated protein 1 (TGFBRAP1) and TGF‐β1 receptor 2 (TGFBR2) with type 2 diabetes mellitus (T2DM), and its genetic effects on diabetes‐related miRNA expression." (PMID 30461200, 2019). "The purpose of this study is to investigate the associations of nine single nucleotide polymorphisms (SNPs) at TGFBR2 and three SNPs at TGFBRAP1 with T2DM and to evaluate its genetic effects on diabetes‐related miRNA expression." (PMID 30461200, 2019). "This indicated that TGFBRAP1 might participate in the epigenetic mechanism of diabetes; however, a further systemic functional analysis would be warranted and future studies of population diversity are desired." (PMID 30461200, 2019).
liver fibrosis (1 paper, 2019). "The TGF-β1/smad signalling pathway can regulate liver homeostasis, although the distinct role of TGFBR2 and TGFBRAP1 in the TGF-β1/smad signalling pathway had been observed previously, playing a vital role in liver fibrosis and hepatocarcinogenesis." (PMID 31534460, 2019).
cancer (3 papers, 2021 to 2024). A tumor composed of atypical neoplastic, often pleomorphic cells that invade other tissues. "For the remaining 17 genes, DNMT3B, RARB, SMAD5, SMARCA5, SMARCC1 and TGFBRAP1 were predicted only by our method, but various evidence suggests that they have a driving role in cancer development." (PMID 39186807, 2024).
tumor (3 papers, 2021 to 2024). "Additionally, TGFBRAP1 plays a pivotal role in modulating the TGF-beta/activin signaling pathway, a pathway intricately linked to tumor development and immune system diseases." (PMID 39186807, 2024).
infection (1 paper, 2017). The state of being infected such as from the introduction of a foreign agent such as serum, vaccine, antigenic substance or organism. "Further, little or no recruitment of TGFBRAP1 on SCVs and SIFs was observed at different time points of infection." (PMID 29084291, 2017).
TGFBRAP1 also shares sentences with these, for which no sentence is quoted: alcoholism (1 paper); atherosclerosis (1); autoimmune disease (1); chronic hepatitis B infection (1); chronic hepatitis C (1); hepatitis C infection (1); immune system diseases (1); liver cancer (1); liver disease (1); malnutrition (1); preeclampsia (1); type 2 diabetes mellitus (1).